SYNPO (synaptopodin)
Description:
Actin-associated protein that may play a role in modulating actin-based shape and motility of dendritic spines and renal podocyte foot processes. Seems to be essential for the formation of spine apparatuses in spines of telencephalic neurons, which is involved in synaptic plasticity (By similarity).
Synonyms: KIAA1029; SYNPO1
Tractability: Antibody: its Gene Ontology location is reachable by antibodies, with high confidence. PROTAC: ubiquitination databases record sites on it; its protein half-life has been measured.
Gene: Protein-coding gene on chromosome 5 (150,601,080 to 150,659,208, forward strand). Ensembl gene ENSG00000171992.
Subcellular location: Cytoplasm, cytoskeleton; Cell junction, tight junction; Perikaryon; Cell projection, dendritic spine; Postsynaptic density; Synapse; Cytoplasm, cytosol
Subcellular location (Human Protein Atlas): Cytosol; Plasma membrane; Actin filaments
Gene Ontology:
Molecular function: protein binding; actin binding
Biological process: positive regulation of actin filament bundle assembly; spine apparatus assembly; postsynaptic modulation of chemical synaptic transmission; regulation of long-term neuronal synaptic plasticity; regulation of postsynaptic cytosolic calcium ion concentration; visual learning
Cellular component: actin cytoskeleton; cytosol; dendritic spine; nucleus; spine apparatus; stress fiber; Z disc; bicellular tight junction; cell periphery; cytoskeleton; glutamatergic synapse; organelle; perikaryon; postsynaptic density; Schaffer collateral - CA1 synapse; synapse
Genetic constraint (gnomAD): Loss-of-function variants: 19 observed, 48.18 expected, observed/expected ratio (o/e) 0.39, 90% interval 0.27 to 0.58. The upper end of that interval is the gene's LOEUF score, 0.58, which puts it in group 2 of 6, group 1 being the genes least tolerant of losing a copy. Missense variants: 1,131 observed, 1,189.9 expected, observed/expected ratio (o/e) 0.95, 90% interval 0.9 to 1. Synonymous variants: 532 observed, 518.37 expected, observed/expected ratio (o/e) 1.03, 90% interval 0.95 to 1.1.
Gene-disease validity (ClinGen):
ClinGen rates the evidence that SYNPO causes each of these diseases.
focal segmental glomerulosclerosis (autosomal dominant): Limited. A renal disorder characterized by sclerotic lesions in the glomeruli.
Homologues: Orthologues: chimpanzee SYNPO (99% identical), macaque NDST1 (98% identical), dog SYNPO (86% identical), rat Myoz3 (84% identical), pig SYNPO (81% identical), mouse Synpo (79% identical), rabbit SYNPO (78% identical), guinea pig SYNPO (62% identical), tropical clawed frog synpo (24% identical), Drosophila melanogaster CG1674 (10% identical). Paralogues in human: SYNPO2 (21% identical), SYNPO2L (16% identical).
Diseases named in the same sentence as SYNPO in open-access papers:
SYNPO is named in the same sentence as 66 diseases in open-access papers, as found by Europe PMC text mining. Sharing a sentence is not in itself a finding about the gene and the disease. The quoted sentences say what the papers report.
glomerular diseases (15 papers, 2009 to 2025). "As glomerular diseases progress, loss of the podocyte foot process is accompanied by loss of podocyte markers such as Podocalyxin (PODXL) and Synaptopodin (SYNPO)." (PMID 35883199, 2022). "Synaptopodin is known to maintain podocyte foot processes and downregulation of the podocyte actin cytoskeleton has been observed in human and rodent glomerular diseases." (PMID 30909435, 2019). "In contrast to Coro2b, staining for synaptopodin, another podocyte specific protein, showed only modest reduction in all three glomerulopathies." (PMID 31221975, 2019). "Recently, some investigators have reported that the levels of the SD and FP proteins, nephrin, podocin, CD2AP, and SYNPO, decrease in glomerular diseases." (PMID 30919150, 2019). "For example, SNPs in SYNPO may influence protein expression levels or function, contributing to glomerular diseases." (PMID 41368354, 2025). "Indeed, subjects affected by glomerulopathy usually present with a reduced expression of podocin and synaptopodin, key molecules for the maintenance of slit-diaphragm function, which is the main unit of the ultrafiltration barrier." (PMID 37627492, 2023). "Furthermore, these authors have highlighted the association between the expression of nephrin, podocin, CD2AP, and SYNPO proteins and the development of glomerular disease." (PMID 30919150, 2019). "Nephrin, podocin, synaptopodin, podocalyxin, CD2AP, ACTN4 (encodes for α-actinin 4), PTPRO (encodes for GLEPP-1), and WT1 mRNA have been isolated from urine of patients with varying glomerulopathies." (PMID 24327929, 2013). "The studies with renal biopsies from patients with acquired human glomerular diseases show correlation, besides in the mRNA expression of Neph3 and nephrin, also in the mRNA expression of nephrin and other podocyte-expressed genes, including synaptopodin and α-actinin-4." (PMID 19703278, 2009). "Quantitative analysis revealed significantly higher CCL5 intensity in FSGS, IgAN, and LN compared with MCD, and the degree of CCL5 and synaptopodin colocalization was also increased, suggesting upregulation of CCL5 in glomerular disease." (PMID 40986444, 2025). "In glomerular disease and most types of CKD, podocyte functional proteins such as nephrin and synaptopodin are dysregulated leading to glomerular dysfunction." (PMID 33782421, 2021). "To find out whether the Dach1 expression is also altered in patients suffering from glomerular disease, we measured the DACH1 mRNA expression of microdissected glomeruli and co‐stained biopsies for DACH1 and synaptopodin." (PMID 29498212, 2018). "This is the reason why the known cytoskeletal regulators of glomerular diseases, such as synaptopodin and actinin 4, were not included among our candidates." (PMID 27227331, 2016). "Data from a study that included patients with a number of different glomerulopathies showed that urine sediment did not stain for synaptopodin." (PMID 24327929, 2013).
diabetes (9 papers, 2013 to 2024). "A similar diabetes-associated decrease in synaptopodin in the kidneys has also been described in db/db mice and this was also normalized by pyridoxamine treatment." (PMID 31451429, 2019). "Hippocampal proteins down-regulated in diabetes and up-regulated by pyridoxamine, include beta-actin and synaptopodin." (PMID 31451429, 2019). "The results show that UAER values significantly increase and synaptopodin protein expression significantly decreases 8 weeks after diabetes onset, indicating a serious injury in podocyte." (PMID 23762850, 2013). "By analogy, immunofluorescence microscopy showed comparable glomerular expression of the podocyte differentiation marker synaptopodin in untreated control, untreated KO and diabetic control mice, but synaptopodin was reduced significantly in IRE1α KO mice with diabetes." (PMID 38778209, 2024). "In our experiments using isolated glomerular samples, low- and high-dose ipragliflozin reduced synaptopodin expression and subsequent oxidative stress within glomeruli; however, only high-dose ipragliflozin ameliorated the diabetes-induced up-regulation of Nox4 in glomeruli." (PMID 29507299, 2018). "In addition to nephrin, other proteins can also be suppressed in the renal tissue and/or be increased in the urine of diabetes subjects, including podocin, podocalyxin, synaptopodin, and Wilms’ tumor protein (WT-1), a phenotypic marker of mature podocytes." (PMID 24103534, 2013). "Furthermore, after 6 months of diabetes, the number of podocytes per glomerulus and the expression of synaptopodin was comparable among untreated (non-diabetic) control, untreated IRE1α KO and diabetic control mice, but diabetic IRE1α KO mice showed a significant reduction." (PMID 38778209, 2024).
diabetic nephropathy (9 papers, 2012 to 2025). "Podocytes injury is one of the leading causes of proteinuria in patients with diabetic nephropathy (DN), and is accompanied by podocytes apoptosis and the reduction of podocyte markers such as synaptopodin and nephrin." (PMID 35069207, 2021). "Dysregulation of synaptopodin is linked to proteinuric kidney diseases, such as FSGS and diabetic nephropathy." (PMID 41368354, 2025). "Data from another study examining patients with diagnosed diabetic nephropathy presented that urinary synaptopodin mRNA correlated with the degree of proteinuria." (PMID 24327929, 2013). "We found statistically significant downregulation of synaptopodin (P<0.0001), podocin (P = 0.0002), and nephrin (P<0.0001) in kidney biopsies of diabetic nephropathy as compared with controls." (PMID 22615747, 2012). "Interestingly, glomeruli of biopsies from patients suffering from diabetic nephropathy showed also a significant reduction of Dach1 and synaptopodin in contrast to control biopsies." (PMID 29498212, 2018). "It was found in diabetic nephropathy patients that urinary synaptopodin mRNA significantly correlated with glomerular podocyte number observed in histologic examination, showing that urinary synaptopodin mRNA may be clinically applicative in monitoring disease progression in these patients." (PMID 24327929, 2013). "DNA methylation and histone modifications can regulate synaptopodin expression, and thus, hypermethylation of the SYNPO promoter has been observed in diabetic nephropathy, leading to reduced synaptopodin levels and podocyte injury." (PMID 41368354, 2025). "Double immunofluorescence staining for both synaptopodin (red) and UCH-L1 (green) revealed that UCH-L1 can be evidently positioned in the podocytes (marked by synaptopodin) of diabetic nephropathy patients." (PMID 27571062, 2016). "Using a streptozotocin model of diabetic nephropathy, urinary cells could be stained against synaptopodin; however, in healthy controls, urinary cells stained for synaptopodin could not be detected." (PMID 24327929, 2013).
glomerulosclerosis (6 papers, 2013 to 2023). A hardening of the kidney glomerulus caused by scarring of the blood vessels. "Glomerular sclerosis and plasminogen/plasmin co-localized with synaptopodin, which is a major podocyte marker that was decreased in the HS group, were observed at 5 weeks." (PMID 37958726, 2023). "Compared with the db/db animals exposed to Ad-NC, the animals challenged with Ad-KL showed ameliorated glomerulosclerosis, decreased podocyte foot process effacement, elevated Synaptopodin expression, and more cells positive for WT-1 in the kidneys." (PMID 35480629, 2022). "We observed clusters of HES1-expressing cells that were positive for the podocyte marker, Synaptopodin, at onset of glomerulosclerosis in mutants compared with controls." (PMID 29398135, 2018). "Infused MSCs repair the podocyte and renal interstitial injury by upregulating synaptopodin expression and downregulating TGF-β1 expression, resulting in that the manifestations such as glomerular sclerosis, mesangial expansion, and tubular dilatation were obviously improved." (PMID 23762850, 2013).
Alzheimer disease (5 papers, 2017 to 2023). A progressive, neurodegenerative disease characterized by loss of function and death of nerve cells in several areas of the brain leading to loss of cognitive function such as memory and language. "Intriguingly, SYNPO mRNA expression levels were found to be low in neurons from persons with Alzheimer’s disease, while a meta-analysis of cognitive trajectories in advanced age identified higher SYNPO protein levels to be associated with cognitive stability." (PMID 36864036, 2023). "Accordingly, alterations in synaptopodin expression and retinoid signaling have been observed in the brain tissue of patients with Alzheimer’s disease and cognitive decline." (PMID 33781382, 2021). "Given that RFX7 has been associated with Alzheimer’s disease and cognitive function, a particularly interesting candidate target is SNYPO encoding for the actin filament regulator synaptopodin, which is important for synaptic plasticity and can facilitate Tau protein degradation." (PMID 36864036, 2023). "Interestingly, our recent data found significant down-regulation of synaptopodin in the brains of people with Alzheimer's disease." (PMID 31451429, 2019). "But also levels of synaptopodin, synaptophysin, synaptotagmins, neurogranin and GAP43 were lower in patients with Alzheimer's disease than in cognitively normal controls." (PMID 28912682, 2017).
lupus nephritis (5 papers, 2013 to 2025). Glomerulonephritis in the context of systemic lupus erythematosus. "In patients with lupus nephritis, urinary synaptopodin mRNA was measured, and as the patients were followed over time, urinary synaptopodin mRNA decreased along with the GFR." (PMID 24327929, 2013). "This may be the evidence to support that urinary synaptopodin mRNA could be a clinically useful biomarker for following disease progression in patients with lupus nephritis since it seems to trend along with the GFR." (PMID 24327929, 2013). "In patients with FSGS, IgA nephropathy (IgAN), and lupus nephritis (LN), CCL5 was highly expressed in the glomeruli and showed a capillary pattern that colocalized with synaptopodin, a podocyte-specific marker." (PMID 40986444, 2025). "Urinary podocyte-specific mRNA markers such as podocalyxin, synaptopodin, podocin, nephrin, as well as WT-1 levels, are significantly elevated in patients with active lupus nephritis compared to those without systemic lupus or active lupus nephritis." (PMID 35886957, 2022).
Nephropathy (5 papers, 2013 to 2025). A nonspecific term referring to disease or damage of the kidneys. "Loss or dysfunction of synaptopodin disrupts the slit diaphragm, leading to proteinuria and progressive kidney damage." (PMID 41368354, 2025). "Flot2 expression in the kidney was also reduced in diabetic db/db mice, and in lipopolysaccharide (LPS)- induced and adriamycin (ADR)-induced nephropathy mice, as shown by double immunostaining of Flot2 and synaptopodin." (PMID 36632460, 2023). "CeA treatment in an adriamycin-induced nephropathy model showed increased podocin, nephrin, and synaptopodin mRNA and protein levels." (PMID 31728118, 2019). "A similar pattern was observed in ADR-induced nephropathy mice, where CCL5 was upregulated in podocytes 3 days after ADR injection, showing a capillary pattern colocalized with synaptopodin." (PMID 40986444, 2025).
nephrotic syndrome (5 papers, 2012 to 2024). A collection of symptoms that include severe edema, proteinuria, and hypoalbuminemia; it is indicative of renal dysfunction. "The damage of podocyte foot processes and loss of slit diaphragm proteins such as nephrin, podocin, and ancillary proteins such as synaptopodin are thought to give rise to the nephrotic syndrome." (PMID 37958544, 2023). "In addition, synaptopodin is an actin-associated protein essential for the integrity of the podocyte actin cytoskeleton because synaptopodin-deficient mice display impaired recovery from protamine sulfate-induced foot process effacement and lipopolysaccharide-induced nephrotic syndrome." (PMID 22693670, 2012). "The aim of the study was to to assess the levels of antibodies targeting synaptopodin and annexin 1 in the blood serum of patients diagnosed with nephrotic syndrome, with the aim of evaluating their potential utility in diagnosing primary podocytopathies and predicting therapeutic response." (PMID 39544697, 2024). "To further confirm glomerular Angptl4 expression in MCD, we stained for Angptl4, desmin and synaptopodin in samples obtained from nephrotic syndrome patients with MCD (n = 15), MN (n = 5), FSGS (n = 5) and mesangial proliferative glomerulonephritis (MsPGN, n = 5)." (PMID 26352670, 2015). "We observed a significant increase in the levels of antibodies to both synaptopodin and annexin 1 in adult patients with MCD and FSGS presenting with nephrotic syndrome, compared to those with membranous nephropathy and healthy individuals." (PMID 39544697, 2024).
autism (4 papers, 2019 to 2025). Persistent deficits in social interaction and communication and interaction as well as a markedly restricted repertoire of activity and interest as well as repetitive patterns of behavior. "Both KLHL17 and SYNPO are F-actin-binding proteins linked to autism." (PMID 37651441, 2023). "Compared with the control group, the mRNA levels of synaptic development‐related genes SYN1, SYNPO, and axon development‐related genes Lingo‐1 were significantly increased in the VPA‐induced autism model group (p < 0.01) and improved after AVP treatment (p < 0.01)." (PMID 36239083, 2022). "Furthermore, in our analysis, several DE miRNA targets were found to be associated with neuropsychiatric disorders, such as schizophrenia (TTN, SYNPO), depressive disorder (PPARGC1B, TIMELESS), and autism (TAF1, TRIO)." (PMID 31652596, 2019).
colitis (4 papers, 2019 to 2025). Inflammation of the colon. "Synaptopodin, found in actin stress fibers and tight junctions in epithelial cells, has been shown to exacerbate colitis in synaptopodin-deficient mice in response to dextran sodium sulfate." (PMID 39596193, 2024).
lupus (4 papers, 2015 to 2025). "We speculate that decreases of synaptopodin in lupus mice may cause ultrastructural changes of foot processes, which disturb their function, eventually leading to fusion of foot processes and their disappearance." (PMID 26161538, 2015). "In vitro treatment with rebamipide showed a trend toward restoring the expression of these proteins, with the most prominent effect observed in Synaptopodin, consistent with the in vivo results from lupus-prone mice." (PMID 40565270, 2025). "The prominent effects of rebamipide on Synaptopodin expression further support its role in reducing proteinuria and improving renal phenotypes in lupus-prone mice." (PMID 40565270, 2025). "Nephrin, podocin, and synaptopodin urine mRNA levels were discovered to be considerably greater in active LN patients compared to those with quiescent lupus, according to a later investigation." (PMID 38313309, 2024). "Inhibition of CaMK4 in lupus-prone models prevent proteinuria and preserve podocyte ultrastructure through the inhibition of synaptopodin degradation." (PMID 31470591, 2019).
cognitive decline (3 papers, 2020 to 2024). "Moreover, the presence of synaptopodin may interfere with this network process under baseline and plasticity-inducing conditions accounting for the previously reported cognitive deficits in synaptopodin-deficient mice and the synaptopodin-related cognitive decline during human aging." (PMID 38247806, 2024). "Compared with those of AD patients with dementia, the levels of synaptic proteins such as synaptophysin and synaptopodin were also shown to be preserved in the brains of female subjects who presented with AD pathology but were resilient to cognitive decline." (PMID 32390822, 2020). "Moreover, recent work suggested a potential role for synaptopodin in neuropsychiatric diseases, such as cognitive decline and autism spectrum disorders." (PMID 38247806, 2024).
dementia (3 papers, 2017 to 2024). Loss of intellectual abilities interfering with an individual's social and occupational functions. "Another study noted reduced density of SYNPO-labeled spine puncta only in AD cases with dementia, while SYNPO-labeled dendritic spines were maintained in pathologically confirmed AD with normal cognition." (PMID 28800743, 2017). "Interestingly, synaptopodin expression was reported to be downregulated in the hippocampus of patients suffering from dementia with Lewy bodies, Parkinson’s disease, mild cognitive impairments, and AD." (PMID 38324617, 2024). "Hence, the reduction of SYNPO probably indicates a declining synaptic function in the prefrontal cortex which may contribute to dementia." (PMID 28800743, 2017).